NEFL (neurofilament light chain)
Diseases named in the same sentence as NEFL in open-access papers (continued):
Sharing a sentence is not in itself a finding about the gene and the disease.
neurodegenerative disease (345 papers, 2008 to 2026). A disorder of the central nervous system characterized by gradual and progressive loss of neural tissue and neurologic function. "One study examines neurofilament light chain (Nf-L) in DPS as a potential early diagnostic marker for neurodegenerative diseases." (PMID 40332506, 2025). "Neurofilament-light chain (NfL) is associated with neurodegenerative diseases, which are increasingly prevalent with aging." (PMID 39346641, 2024). "This review discusses the link between neurofilament light chain (NfL) involvement in psychiatric and neurodegenerative diseases and gives insights into the diagnostic and prognostic value of NfL in SMDs." (PMID 39795920, 2024). "As for many other neurodegenerative diseases, neurofilament light chain (NfL) is shown to be increased in preataxic mutation carriers already 7.5 years before disease onset also in SCA3 even correlating with disease severity." (PMID 33106888, 2021). "Reduced organelle trafficking is implicated in multiple neurodegenerative diseases and in selective length-dependent degeneration of the longest axons as well as with dominant NEFL missense mutations." (PMID 35237613, 2021). "Increased neurofilament light chain (NfL) levels in the CSF are associated with neuronal and axonal degeneration, and have been reported in patients with neurodegenerative diseases, particularly in patients with probable TDP43 pathology." (PMID 27915998, 2016). "Increased neurofilament light chain (NfL) levels in the CSF, which are associated with neuronal and axonal degeneration, have been reported in patients with neurodegenerative diseases, and more specifically in patients with probable TDP-43 pathology such as svPPA patients." (PMID 30186225, 2018). "Plasma neurofilament light chain (NfL), an established biomarker of axonal damage, helps monitor the progression of neurodegenerative disease." (PMID 41406487, 2025). "We also assessed the association of the synaptic proteins with established biomarkers of neurodegenerative disease pathology (beta-amyloid (Aβ) 1–42 and 1–40, ptau, total tau, neurofilament light chain (NfL)) to study aetiopathogenic aspects." (PMID 40840974, 2025). "Neurofilament light chain (NFL) is a well-established biomarker for several neurodegenerative diseases, serving as an indicator of axonal damage or neuronal degeneration." (PMID 40773095, 2025). "This accelerated approval was based on reductions in plasma neurofilament light chain (NfL) levels, a biomarker for neurodegenerative diseases." (PMID 40234983, 2025). "Elevated levels of neurofilament light chain (NFL) in serum or cerebrospinal fluid, a biomarker used in neurodegenerative disease diagnostics, have also been associated with CIPN caused by agents such as oxaliplatin or taxanes." (PMID 41123671, 2025). "Neurofilament light chain (NfL) is a protein and considered to be a biomarker for several neurodegenerative diseases." (PMID 40004604, 2025). "Neurofilament light chain (NfL), measurable in both cerebrospinal fluid and plasma, has emerged as a sensitive marker of axonal injury, useful for distinguishing neurodegenerative diseases from primary psychiatric conditions." (PMID 40507935, 2025). "A well‐known clinical biomarker of neurodegenerative diseases is the neurofilament light chain (NfL), which is exclusively expressed in neurons and highly specific for neuronal cell damage." (PMID 40119726, 2025). "Predictive algorithms developed using APOE genotyping, tau-PET imaging, and plasma neurofilament light chain (NfL) levels are leading to earlier diagnoses of neurodegenerative diseases and further enhancing the application of targeted therapies." (PMID 40806492, 2025). "In CSF, the neurofilament light chain (NfL) and total tau (t-tau) have emerged as markers of axonal degeneration observed in neurodegenerative diseases." (PMID 39767701, 2024).
neurodegenerative disease (continued). "The levels of neurofilament light chain (NfL) are highly correlated between serum and CSF, making serum NfL (sNfL) an increasingly utilized biomarker in neurodegenerative diseases." (PMID 38407594, 2024). "Neurofilament light chain (NfL) has been one of the potential peripheral biomarkers related to neurodegenerative diseases." (PMID 38627748, 2024). "Plasma neurofilament light chain (NfL) is a promising biomarker of neurodegeneration with potential clinical utility in monitoring the progression of neurodegenerative diseases." (PMID 38664843, 2024). "Biomarkers reflecting brain amyloid beta accumulation (plasma Aß42/40 ratio), pathologic tau protein (p-tau231, p-tau181, p-tau217), and neurodegeneration (neurofilament light chain (NfL)) have advanced the diagnosis of AD and other neurodegenerative diseases." (PMID 37233882, 2024). "Neurofilament light chain (NfL) has been identified as reliable fluid biomarker for neuroaxonal damage in neurodegenerative diseases, with first studies showing higher NfL levels in MSA compared to PD." (PMID 39254698, 2024). "Neurofilament light chain (NfL) is a neuronal cytoplasmic protein that forms part of the cytoskeleton and has gained attention over recent years for the diagnosis of neurodegenerative diseases, including AD." (PMID 37240322, 2023). "Recent research has focused on neurofilament light chain (NfL) as a potential biomarker for neurodegenerative diseases, including AD." (PMID 37838690, 2023). "The neurofilament light chain (NFL), a blood biomarker of neuroaxonal damage in several neurodegenerative diseases, represents a potential biomarker for DSPN." (PMID 36472640, 2023). "Neurofilament light chain (NfL) levels are a protein-indicator of axonal damage and serve as a biomarker for several neurodegenerative diseases, including PD." (PMID 36077138, 2022). "NEFL mRNA has been found to be altered in other neurodegenerative diseases, such as ALS, and this finding in the hippocampus supports a different response in this area to prion-associated pathogenesis." (PMID 35806183, 2022). "Plasma neurofilament light chain (NEFL), a previously reported biomarker of several neurodegenerative diseases, has been shown to be increased in mouse models and patients with various genetic forms of CMT." (PMID 35148379, 2022). "Blood-based neurofilament light chain (NfL) is a promising biomarker of neurodegeneration across multiple neurodegenerative diseases." (PMID 36527130, 2022). "Among biomarker candidates for neurodegenerative diseases, α-synuclein, and neurofilament light chain (NFL) are the two most studied molecules in PD." (PMID 34858161, 2021). "Recently, quantitative magnetic resonance imaging (MRI) and neurofilament light chain (NFL) emerged as valuable tools to track the progression of some neurodegenerative diseases and uncovering their pathophysiology." (PMID 34538260, 2021). "The neurofilament polypeptides encoded by NEFH, NEFM, and NEFL are promising protein biomarkers for ALS and other degenerative diseases." (PMID 34511133, 2021). "Neurofilament-light chain (NF-L) is a well-known clinical biomarker of many neurodegenerative diseases." (PMID 32595447, 2020). "During the last years, Neurofilament-light chain (NF-L) has been shown to be a valuable biomarker for several neurodegenerative diseases." (PMID 32595447, 2020). "Apart from this, insufficient axon transport is a common theme in many neurodegenerative diseases, and some researches have found that NEFL and HSPB1 (included in the GO term of axon transport) are closely related to axonal transport dysfunction of CMT." (PMID 33029488, 2020). "Results on metabolic pathways support an alteration of the Neurodegenerative Diseases and Nervous system C2 classes with the most frequently associated differentially expressed genes in the BSP (BAD, NEFH, NDUFB2, DERL1, NEFL)." (PMID 23782433, 2013).
neurodegenerative disease (continued). "Serum Neurofilament Light chain (NfL) is a promising biomarker of neuronal damage, used to assess the extent of neuronal injury and neurodegeneration, and it is widely applied in the diagnosis of neurodegenerative disease and monitoring disease progression." (PMID 39906713, 2025). "Additionally, plasma glial fibrillary acidic protein (GFAP) and neurofilament light chain (NfL) have emerged as potential biomarkers for AD and other neurodegenerative diseases, further expanding the potential of blood‐based diagnostics." (PMID 40613333, 2025). "Furthermore, neurofilament proteins, such as neurofilament light chain (NfL), haven proven to be important markers of neuro-axonal injury in many neurodegenerative diseases." (PMID 39195261, 2024). "NF-light is a family of filament proteins, which mainly exist in the axons of nerve cells and participate in the formation and maintenance of the cytoskeleton, and the level of neurofilament light chain in the cerebrospinal fluid can be used as a biomarker for neurodegenerative diseases." (PMID 38404286, 2024). "In addition, plasma neurofilament light chain (NfL), a marker of axonal damage, increases in various neurodegenerative diseases, and plasma glial fibrillary acidic protein (GFAP) is a marker of reactive astrogliosis and is elevated in the early stages of AD." (PMID 37480401, 2023). "Another important issue is the potential relationship between serum sTREM2 levels, metabolic markers, and biomarkers involved in neurodegenerative diseases, such as the amyloid-β42/amyloid-β40 ratios, p-tau181 levels, and levels of the neurofilament light chain." (PMID 35592778, 2022). "Neurofilament light chain (NfL) is a novel biomarker of neurodegenerative diseases." (PMID 33230211, 2020). "Additionally, studies have reported that CSF p-tau and t-tau are reduced in PSP, and that the neurofilament light chain is remarkably increased compared to healthy controls and patients with AD, even though PSP is a neurodegenerative disease associated with tau accumulation." (PMID 39335355, 2024). "Quantitative methods for neurofilament light chain in human biofluids have relied on immunoassays, which have limited capacity to describe the structure of the protein in CSF and how this might vary in different neurodegenerative diseases." (PMID 38707707, 2024). "As the field of CSF diagnostics evolves, other biomarkers are being evaluated that may offer further insights into neurodegenerative diseases, including neurofilament light chain (NfL), a marker of neuronal injury, and glial fibrillary acidic protein (GFAP), a marker of astrocyte activation." (PMID 39703457, 2024). "In addition, post-synaptic proteins, such as neurogranin and neuroligin-1, and cytoskeletal proteins, such as neurofilament light chain, were also investigated in CSF as markers of synaptic or cytoskeletal dysfunction, occurring in the brains of patients with neurodegenerative diseases." (PMID 35448530, 2022). "These pathways were, in general, shared across all neurodegenerative diseases, even though the major overlap was found for the synaptic functions (BDNF, CCL2, ACHE, GFAP, NEFH or NEFL) and microglia pathways (TREM2, IL13, IL6R IFNG)." (PMID 41250190, 2025). "Neurofilament light chain (NEFL) is a neuron-specific structural protein, and its serum levels are correlated with the severity of inflammation in neurodegenerative diseases, making it a potential biomarker for these conditions." (PMID 40277545, 2025). "Neurofilament light chain (NfL), a non-disease specific marker for the intensity of ongoing axonal damage, has also demonstrated potential as a blood-based biomarker in neurodegenerative diseases including AD." (PMID 40247130, 2025). "Saliva concentrations of neurodegenerative disease biomarkers such as total tau (t-tau) and neurofilament light chain protein (NfL) are not disease specific for AD and do not correlate to plasma AD biomarkers." (PMID 39606384, 2024).
neurodegenerative disease (continued). "Neurofilament-light chain (Nf-L) is a non-specific early-stage biomarker widely studied in the context of neurodegenerative diseases (NDD) and traumatic brain injuries (TBI), which can be measured in biofluids after axonal damage." (PMID 37511382, 2023). "High levels of neurofilament light chain (NfL) in CSF and blood show high sensitivity for identifying patients with neurodegenerative diseases compared to healthy controls, but this is neither specific to bvFTD nor to tau or TDP-43 in general." (PMID 35992608, 2022). "In addition to Aβ and tau proteins, CSF neurofilament light chain (NFL), a component of myelinated axons, has also recently been identified as a sensitive biomarker of neuronal injury in HIV infection and multiple other neurodegenerative diseases." (PMID 34452054, 2021).
neurological diseases (335 papers, 2013 to 2026). "A cross-disease blood-based biomarker that is highly sensitive to neuronal damage is neurofilament light chain (NfL), which has been associated with disease severity and prognosis in multiple neurological diseases and general neurodegeneration." (PMID 39251725, 2024). "Over the past two decades, an increasing number of studies have shown that neurofilament light chain (NFL) is associated with axonal injury or degeneration, and its CSF concentration has been found to be increased in various neurological disorders." (PMID 36552981, 2022). "Recently, neurofilament light chain (NfL) was reported to be increased in CSF in patients with ALS compared with other neurological diseases, and is suggested to be not only a diagnostic biomarker but also a predictor of disease progression." (PMID 34193068, 2021). "The cerebral biomarkers S100B, neuron specific enolase, (NSE), tau protein and neurofilament light chain (NfL) have proven useful as predictors and diagnostic tools in other neurological disorders." (PMID 33556141, 2021). "Neurofilament light chain (NfL) has been found to be elevated in cerebrospinal fluid (CSF) and blood in neurological diseases associated with axonal injury or degeneration." (PMID 33925126, 2021). "Elevated blood neurofilament light chain (NfL), which indicates the loss of neuronal integrity, is increasingly implicated as a diagnostic and outcome-predicting biomarker for neurological diseases." (PMID 34768602, 2021). "Given its specific expression in neurons and its established diagnostic value in other neurological diseases, neurofilament light chain (NFL) may serve as a useful biomarker for CIPN and warrants further evaluation." (PMID 41123671, 2025). "The advancements in assays for the detection of neuroglial markers of damage, such as neurofilament light chain and glial fibrillary acid protein, have led to a growing interest in their investigation in neurological disorders." (PMID 41947803, 2026). "Neurofilament light chain (NfL), a structural protein of myelinated axons, is a well-established marker of neuronal injury and axonal degeneration in a wide range of neurological disorders." (PMID 41596455, 2026). "Neurofilament light chain protein (NfL) is an intermediate filament used to assess axonal damage across neurological disorders." (PMID 40454659, 2025). "Serum neurofilament light chain (sNfL) is an emerging biomarker of neuronal damage in various neurological disorders." (PMID 40792526, 2025). "Neurofilament light chain (NfL), a protein extensively expressed in neuronal axons, has been identified as a biomarker of some neurological diseases." (PMID 40371084, 2025). "Serum neurofilament light chain (sNfL) is a promising blood-based biomarker for detecting neuroaxonal injury, with elevated levels observed in various neurological disorders." (PMID 40717996, 2025). "So far, neurofilament light chain (NfL) as a biomarker for neuroaxonal damage is one of the most intensively studied biomarker in neurological diseases." (PMID 39859463, 2025). "Blood neurofilament light chain (NfL) is a sensitive biomarker of axonal injury and neurodegeneration, whose levels are increased in AD and other neurological disorders." (PMID 39980634, 2025). "Neurofilament light chain (NfL) is a biomarker for axonal damage in neurological disorders affecting the central and peripheral nervous system." (PMID 40411538, 2025). "Background and aims: Neurofilament light chains (NfL) are neuron‐axonal proteins whose serum concentrations serve as biomarkers for neurological diseases." (PMID 40542608, 2025). "Plasma extracellular vesicles (EVs) offer a promising platform for biomarker development, with neurofilament light chain (NfL) emerging as a potential candidate for neurological diseases." (PMID 39652080, 2025). "Serum neurofilament light chain (sNfL) has emerged as a promising biomarker for a multitude of nervous system disorders." (PMID 38308244, 2024).